IL33 (interleukin 33)
Diseases named in the same sentence as IL33 in open-access papers (continued):
Sharing a sentence is not in itself a finding about the gene and the disease.
non-small cell lung carcinoma (22 papers, 2016 to 2025). A group of at least three distinct histological types of lung cancer, including non-small cell squamous cell carcinoma, adenocarcinoma, and large cell carcinoma. "Zinc finger protein 263 promotes the malignant progression of non-small cell lung cancer by up-regulating interleukin 33 and inhibiting autophagy." (PMID 39717098, 2024). "Previously, it has been shown that glycolysis and GLUT1 expression were upregulated in the IL–33/ST2 pathway in non-small cell lung cancer patients compared to control tissues." (PMID 38255771, 2024). "A prvious study found that the IL-33/ST2 axis enhances lung-resident CD14+ monocyte function in patients with non-small cell lung cancer." (PMID 37719702, 2023). "The increased level of IL-33 was also observed in patients with non-small-cell lung carcinoma (NSCLC) and epithelial ovarian cancer." (PMID 34209038, 2021). "This is in concert with the findings in non-small cell lung cancer 28 and malignant salivary gland tumor patients 19 and is the first evidence to exhibit a high IL-33 in CCA microenvironment as a good prognosis marker." (PMID 33046978, 2020). "Blockade of IL-33 abrogates the polarization of TAMs into (alternatively activated) M2 macrophages in a model of human non-small-cell lung cancer." (PMID 30483263, 2018). "Sera and bronchoalveolar lavage fluid (BALF) taken prior to chemotherapy from patients diagnosed with non-small cell lung cancer (NSCLC) were analyzed by enzyme linked immunosorbent assay (ELISA) to assess circulating levels of IL-27, IL-29, IL-31, and IL-33." (PMID 30205617, 2018). "Infection with the gram-negative E.Coli has been associated with tumor growth, progression and metastasis of non-small cell lung cancer, by promoting lipid synthesis through the TLR4/9 pathway and, also, by facilitating cancer stem cell properties through the TLR4/IL-33 pathway." (PMID 35366267, 2021). "In contrast, IL-33 could be a good survival prediction marker as its the high level was correlated with long overall survival time in non-small cell lung cancer 28, malignant salivary gland tumor 19 and large bile duct CCA patients." (PMID 33046978, 2020). "Similarly, expression of IL-33 was found to be increased when compared to adjacent healthy tissue in patients with both non-small-cell lung carcinoma (NSCLC) and epithelial ovarian cancer." (PMID 31231372, 2019). "For example, it was recently shown that monoclonal antibody blockade of IL-33 in mice xenografted with human non-small-cell lung carcinoma (NSCLC) decreased the accumulation of TREG cells and reduced macrophage M2 polarization, leading to the efficient inhibition of tumor growth." (PMID 30949175, 2019). "IL-33, on the other hand, accelerates Th2-associated cytokine synthesis and upregulates glucose transporter protein 1 (GLUT1) through the IL-33/ST2 pathway to enhance glucose uptake and glycolysis in tumor cells, while promoting growth and metastasis of non-small cell lung cancer." (PMID 36588722, 2022). "IL-33 is elevated in human BRCA and non-small cell lung cancer (NSCLC) tissues compared to adjacent non-tumor tissues." (PMID 39911848, 2025).
acute kidney injury (21 papers, 2014 to 2025). Sudden and sustained deterioration of the kidney function characterized by decreased glomerular filtration rate, increased serum creatinine or oliguria. "The inflammatory factors associated with acute kidney injury, such as IL-6, IL-6R, IL-17, and IL-33, also showed significantly decreased expression levels by DB03476 administration." (PMID 41516327, 2025). "Inflammatory markers released during graft reperfusion, such as galectin-3 and IL-33, have been implicated in cardiac remodeling following acute kidney injury (AKI)." (PMID 40218153, 2025). "In the context of the kidney, IL-33 has been implicated in the development and progression of several diseases etiologies, including acute kidney injury, CKD, glomerulonephritis, and renal allograft fibrosis." (PMID 38899206, 2024). "Considering that IL-33 can cause cardiomyopathy following acute kidney injury, it is possible that it was causally involved in the induction of adverse cardiac function during the initiation phase of CKD in our model." (PMID 39472324, 2024). "In LT, serum levels of IL-33 immediately after reperfusion are associated with postreperfusion syndrome, acute renal failure, and graft function." (PMID 34621275, 2021). "The effect of IL-33 deficiency on acute kidney injury (AKI) and cancer growth was studied in a four-week model of cisplatin-induced AKI in mice with cancer." (PMID 30205617, 2018). "Emerging evidence points to the important roles of interleukin‐33 (IL‐33) in acute kidney injury, yet its contribution to DN is still unclear." (PMID 39465143, 2024). "Recent studies have revealed the potential applications of IL-33 for treating acute kidney injury in preclinical animal models." (PMID 32102434, 2020). "Recently, we demonstrated a role for IL-33 in promoting Treg responses, such that IL-2 and IL-33 can synergize to increase Tregs and protect from experimental acute kidney injury." (PMID 31191312, 2019). "Another role for IL-33 was demonstrated by Akcay and colleagues, finding that IL-33 promotes acute kidney injury (AKI), through CD4 T cell-mediated production of the pro-inflammatory chemokine CXCL1." (PMID 30769901, 2019). "For example, recombinant IL-33 (rIL-33) treatment can exacerbate cisplatin-induced acute kidney injury by increasing CD4+ T cell infiltration, CXCL1 production, and acute tubular necrosis." (PMID 26943125, 2016). "Additionally, in mice, exogenous IL-33 leads to further kidney damage, but exogenous sST2 leads to renal protection in mice after cisplatin-induced acute kidney injury." (PMID 35800259, 2022). "IL-33 also contributes to the pathogenesis of cisplatin-induced acute kidney injury." (PMID 26943125, 2016). "In addition, IL-33 promotes acute kidney injury through CD4 T cell-mediated production of CXCL1." (PMID 27579324, 2016). "In addition, in folic acid-induced acute kidney injury (AKI) models, IL-33 level is increased, and Fer-1 decreases circulating IL-33 levels in AKI." (PMID 34717678, 2021). "Previous studies showed that IL-33 exacerbates acute kidney injury, whereas IL-33 showed a negative correlation with biomarker of kidney injury, such as CRE and urea in gout patients." (PMID 27579324, 2016). "Indeed, in a mouse model of acute kidney injury (AKI), sharing the occurrence of cell damage with kidney IRI, immunofluorescence staining revealed IL-33 expression on the endothelial surface of blood vessels, as well as in glomeruli and in peritubular capillaries." (PMID 24586382, 2014).
Crohn disease (20 papers, 2008 to 2025). A gastrointestinal disorder characterized by chronic inflammation involving all layers of the intestinal wall, noncaseating granulomas affecting the intestinal wall and regional lymph nodes, and transmural fibrosis. "The role of IL-33 in promoting intestinal fibrosis in a mouse model of Crohn’s disease-like ileitis has also been reported." (PMID 38590952, 2024). "IL-33 concentrations are increased in inflamed colonic mucosa and serum and correlated with disease activity in Crohn’s disease in humans." (PMID 38590952, 2024). "Association of IL33 and IL1RL1 genes markers with Crohn’s disease (CD); case-control study." (PMID 23634226, 2013). "The IL-33/ST2 axis regulates the contributions of nucleotide-binding oligomerization domain-containing 2 and ILC2s to early events in Crohn’s disease pathogenesis." (PMID 36291105, 2022). "In summary, the IL-33/ST2 pathway may be an important regulator of UC, but be of less importance in Crohn's disease." (PMID 21871091, 2011).
endothelial dysfunction (20 papers, 2012 to 2026). In vascular diseases, endothelial dysfunction is a systemic pathological state of the endothelium (the inner lining of blood vessels) and can be broadly defined as an imbalance between vasodilating and vasoconstricting substances produced by (or acting on) the endothelium. "Endothelial dysfunction is the hallmark feature in the development of early atherosclerotic lesions, and IL-33 has been reported to be involved in endothelial cell activation, leading to an exacerbation of inflammation." (PMID 36552551, 2022). "We therefore hypothesized that maladaptive IL-33/ST2 signaling may contribute to glomerular damage in T2D by causing endothelial dysfunction." (PMID 38899206, 2024). "Moreover, interleukin-33 (IL-33) and interleukin 1 receptor-like 1 (IL-1RL1; sST2) are linked to endothelial dysfunction and therefore higher cardiovascular risk." (PMID 38673616, 2024). "IL-33 seems to be the most important cytokine for the Th2-mediated host defense and implicated in controlling immune responses to the early events of the inflammation and endothelial dysfunction." (PMID 31156780, 2019). "Therefore, the association of increased inflammation with endothelial dysfunction and poor cardiovascular outcomes in these patients may be mediated by IL-33/ST2 activation." (PMID 28614418, 2017). "We identified a protective mechanism, whereby BMP9 upregulates the decoy receptor sST2, thereby antagonizing IL-33 signaling and mitigating endothelial dysfunction." (PMID 41564150, 2026). "In summary, our findings offer an alternative yet complementary perspective, highlighting the potential of targeting IL-33 signaling as a strategy to mitigate endothelial dysfunction in PAH." (PMID 41564150, 2026). "IL-33, a member of the recently discovered IL-1 cytokine family, is highly expressed in human atherosclerotic plaques.IL-33 is involved in the pathophysiology of vascular diseases through endothelial dysfunction and VSMC migration." (PMID 37046189, 2023). "The IL-33-driven mechanism (IL-33/ST-2/NETs-axis) eventually culminates in endothelial dysfunction and the localized amplification of inflammation in the intima of the arteries, leading to plaque destabilization." (PMID 36552551, 2022). "IL-33 has also been identified as another target of NFATc1 that mediates endothelial dysfunction and vascular wall remodeling, providing a new direction for the study of NFAT-related targeted therapy for atherosclerosis." (PMID 33791348, 2021). "Baicalein displayed anti-inflammatory effects by attenuating endothelial dysfunction and the inflammatory mediators, such as IL-33, IL-6, IL-1β, MMP-9, and IL-13, in radiation enteropathy." (PMID 31474856, 2019). "We examined the changes in IL-33/ST2 levels in CKD patients, as well as the association with a surrogate of endothelial dysfunction." (PMID 28614418, 2017). "The kidney eNOS/ET-1 ratio was significantly higher in the infected IL-33-/- mice, implying that deficiency in DAMP molecule IL-33 alleviated the endothelial dysfunction in the kidneys of Orientia-infected mice." (PMID 26943125, 2016). "Elevated IL-33 on admission correlated positively with vWF-A2 and estimated glomerular filtration rate, and negatively with angiopoietin-1, suggesting links between inflammation, endothelial dysfunction, and early renal involvement." (PMID 41745779, 2026). "LMCD1 mediates IL-33 expression, which plays a role in endothelial dysfunction." (PMID 39967738, 2025). "Supporting this hypothesis, we discovered an IL-33-mediated positive feedback loop between circulating factors of inflammation and endothelial dysfunction in HGMECs." (PMID 38899206, 2024). "Therefore, we looked for the involvement of adherens junction proteins in IL-33-mediated endothelial dysfunction." (PMID 36899839, 2023).
endothelial dysfunction (continued). "An increase in IL-33 expression was observed in atherosclerotic plaques, and thrombin-induced interleukin-33 expression plays a role in endothelial dysfunction, stimulates vascular endothelial damage, is involved in regulating HASMC proliferation and migration, and promotes vascular wall remodeling." (PMID 33791348, 2021). "An increase in the level of IL-33 synthesized in the endothelium and EAT thickness may be indicative of the pathogenic processes associated with CVD, namely endothelial dysfunction and lipid metabolism disorders." (PMID 29548286, 2018). "We found evidence for increased EC stress and endothelial dysfunction in the kidneys of Orientia-infected, IL-33-injected mice, including a significantly reduced Ang1 expression and a near 2-fold increase in Ang2/Ang1 ratio, which was accompanied with a significantly reduced eNOS/ET-1 ratio." (PMID 26943125, 2016). "How the IL-33 levels play a role in TAO may arise from the endothelial dysfunction." (PMID 31156780, 2019). "This study demonstrates that IL-33 is significantly upregulated in PAECs from patients with PAH and in pulmonary vessels of Su/Hx mice, contributing to endothelial dysfunction via EndMT." (PMID 41564150, 2026). "The studies reviewed highlight a multifactorial process involving inflammatory agents such as CRP, S100 proteins, IL-18, IL-33, TNF, and osteopontin, alongside impaired HDL function, endothelial dysfunction, and altered immune cell profiles." (PMID 40943152, 2025). "It has been shown that the IL-33/ST2 signaling pathway is activated in diabetic nephropathy, and endothelial dysfunction can be induced during the development of diabetic nephropathy." (PMID 35095557, 2021). "In our study, it was also shown for the first time that IL-33 and ST2 had an effect on endothelial dysfunction in patients with kidney disease; these findings also support other patient populations." (PMID 28614418, 2017). "In our study, it was found that increased IL-33 and ST2 levels were associated with endothelial dysfunction, ST2 was one of the predictors of endothelial dysfunction, and both IL-33 and ST2 were predictors of fatal and nonfatal cardiovascular events during the follow-up period of the patients." (PMID 28614418, 2017). "Serum IL33 is higher in AP compared to HC; conversely a reduction of PBP of hands was present in AP compared to HC, probably due to endothelial dysfunction, strictly dependent on acromegaly and are not influenced by the choice of treatment." (PMID 38329608, 2024).
type 2 diabetes (20 papers, 2011 to 2025). "Lastly, in a cohort study of type 2 diabetes and control subjects, gene expression of IL-33 in subcutaneous tissue was higher in type 2 diabetes than controls and was associated with insulin resistance." (PMID 39200943, 2024). "However, IL-33 administration improves glucose tolerance, which is associated with the accumulation of M2 macrophages in adipose tissue of ob/ob mice that are the mutant mice to construct the model of Type II diabetes." (PMID 30761089, 2019). "Manipulating IL-33 expression to induce Th2 cytokines and promote macrophage polarization may offer a promising therapeutic strategy for treating or preventing type 2 diabetes in obese patients." (PMID 40236667, 2024). "Similarly, in adipose tissue, stromal cell–derived IL-33 stimulates the release of pathological type 2 immune cytokines, which impair visceral adipose tissue homeostasis and contribute to type 2 diabetes mellitus." (PMID 34699382, 2021). "In type 2 diabetic (T2D) mice induced by a combination of a high‐fat diet (HFD) and streptozocin (STZ), both circulating and mRNA levels of IL‐33 and ST2 were also elevated." (PMID 39465143, 2024). "Whereas, in the context of T2D, researchers have noted reduced IL-33 expression in the adipose tissue of patients with both prediabetes and type 2 diabetes compared with those without metabolic disease." (PMID 39171751, 2024). "In individuals with normal glycemia, NFAT5 correlates with IL33/ST2, while in type 2 diabetes mellitus (T2DM), it inversely correlates with body fat percentage and directly correlates with soft lean mass percentage." (PMID 40421201, 2025).
depression (19 papers, 2014 to 2026). "Disturbed mitochondrial-associated protein mRNA expression circadian rhythms are associated with IL-33-induced depression-like behavior." (PMID 40076523, 2025). "Genetic evidence indicates that higher IL-33 mRNA expression in hippocampal tissue is linked to depression-like behaviors." (PMID 40076523, 2025). "The present study has revealed that IL-33 plays a regulatory role in circadian rhythms and is associated with depression-like behaviors." (PMID 40076523, 2025). "It is suggested that the altered circadian rhythm activity is associated with depression-like behavior in IL-33-overexpressing mice." (PMID 40076523, 2025). "IL-33, a member of the IL-1 family of cytokines, is also important in the neuroinflammatory landscape associated with depression." (PMID 40305200, 2025). "IL-33’s effect on synaptic remodeling in microglia and astrocytes affects emotion-related brain areas, potentially influencing depression risk." (PMID 39273641, 2024). "Changes in circulating ST2 levels reveal a positive link with lower depression risk, consistent with IL-33 effects." (PMID 39273641, 2024). "Increased levels of circulating IL-33 are linked to a decreased incidence of depression, and IL-33 corresponds with a lower recurrence rate in MDD and BD electroconvulsive treatment." (PMID 39273641, 2024). "Particularly among women with a history of childhood maltreatment, some single-nucleotide polymorphism (SNP) haplotypes in the IL-33 gene, such as rs11792633 and rs7044343, offer protection against depression." (PMID 39273641, 2024). "Taken together, the results reviewed support the evidence that elevated levels of IL-33 are associated with acute symptoms in affective disorders and schizophrenia, and with recurrence in depression." (PMID 33810498, 2021). "During the first few hours of Mcc HN-B infection, IL-33 may be largely produced and cause pulmonary inflammation, which could explain the symptoms of depression and inappetence to some extent." (PMID 39061526, 2024). "However, there have been reports of an association of IL-33 with recurrent miscarriages, as well as a study conducted in a group of pregnant women with depression showing elevated levels of IL-33." (PMID 39065188, 2024). "This raises the possibility of IL-33 as a depression diagnostic and treatment tool." (PMID 39273641, 2024). "IL-33, which shows high expression in glial cells and astrocytes, has been associated with neurological diseases such as Alzheimer’s, post-traumatic stress disorder, major depressive disorder, and schizophrenia." (PMID 38835777, 2024). "In response to these divergent results, we conducted a review and meta-analysis aimed at resolving published research on the correlation between IL-33 and depression risk, and understanding the potential role of IL-33 in the development and treatment of depression." (PMID 38025419, 2023). "Therefore, the change of IL-33 level in serum and cerebrospinal fluid can serve as useful indicators for assessing the risk of depression, and the biomarker provides potential treatment strategies for reducing the burden of the disease." (PMID 38025419, 2023). "Currently, research on the correlation between IL-33 and depression risk is inconsistent." (PMID 38025419, 2023). "Our meta-analysis showed that IL-33 had a positive correlation with reduced risk of depression." (PMID 38025419, 2023). "Furthermore, according to the subgroup analysis of depression-related data sources for disease or treatment, the correlation between IL-33 and depression risk is reflected throughout the entire process of depression development and treatment." (PMID 38025419, 2023). "Moreover, there is evidence for the role of IL-33 in neuroinflammatory processes in the major depressive disorder as well as in depression risk." (PMID 37759873, 2023). "Higher concentrations of IL-33 in cerebrospinal fluid have been associated with depression." (PMID 32486265, 2020).